PSMD14 (proteasome 26S subunit, non-ATPase 14)
Diseases named in the same sentence as PSMD14 in open-access papers (continued):
Sharing a sentence is not in itself a finding about the gene and the disease.
tumor (continued). "Although existing research suggests that lipid deposition in the tumor microenvironment plays a significant role in immune resistance and immune cell function, the specific role of PSMD14 in this process remains to be explored." (PMID 41051446, 2025). "More critically, knockdown of PSMD14 inhibited PC cell proliferation, migration, and invasion in vitro and suppressed PC tumor growth and lung metastasis in vivo." (PMID 40066751, 2025). "Inhibition of PSMD14 exhibited significant anti-tumor efficacy, underscoring its potential for clinical translation in LUAD treatment." (PMID 41488674, 2025). "Despite significant progress in the comprehension of tumor biology, a crucial gap persists in clarifying the contributions of specific molecular entities, such as PSMD14, within the tumor immune microenvironment and their relevance to patient prognoses." (PMID 40475775, 2025). "The current investigation focuses on the expression levels of PSMD14 in LUAD and its complex association with the tumor immune microenvironment, as well as its implications for patient prognosis." (PMID 40475775, 2025). "The results indicate a substantial correlation between elevated levels of PSMD14 expression and tumor progression, as well as adverse patient prognosis, thereby offering fresh perspectives on its viability as a biomarker." (PMID 40475775, 2025). "In vivo studies demonstrated that PSMD14 silencing significantly inhibited tumor formation, whereas PSMD14 overexpression accelerated subcutaneous tumor growth, as shown by weight and tumor volume measurements." (PMID 41051446, 2025). "This study reveals a previously unrecognized role of PSMD14‐derived lactate in mediating histone lactylation‐coupled lipid deposition and tumor progression." (PMID 41051446, 2025). "Our investigation into immune cell infiltration underscores the pivotal role of PSMD14 within the tumor microenvironment of LUAD." (PMID 40475775, 2025). "Through functional approaches in in vitro and in vivo models it has been demonstrated that RPN11/PSMD14 supports tumor aggressive features through a mechanism that involves Leucine Rich Pentatricopeptide Repeat Containing (LRPPRC)." (PMID 39430244, 2024). "In general, PSMD11 and PSMD14 are closely related to tumor development and poor prognosis, however few studies in the context of AML are lacking." (PMID 38482057, 2024). "and that PSMD14 overexpression was related with vascular infiltration, tumor metastasis, tumor recurrence, and survival." (PMID 37853322, 2023). "The expression of USP14, USP21 and PSMD14 significantly increases within tumor tissue from liver cancer patients, which is negatively correlated with survival rate." (PMID 37251574, 2023). "Second, we discovered that the PI3K/Akt/m-TOR signaling pathway plays a crucial role in PSMD14-mediated tumor cell progression in OS; however, further research is required to identify the intermediate involved." (PMID 38053170, 2023). "PSMD14 knockdown inhibits in vitro cell proliferation, migration, invasion, and in vivo tumor growth." (PMID 38053170, 2023). "Our results showed that PSMD14 depletion can inhibit BC tumor cell growth by decreasing GPX4, and high expression of PSMD14 is an independent risk factor for worse DFS in BC." (PMID 36632137, 2023). "The findings demonstrated that the level of PSMD14 was not only substantially related to pathological tumor grade and advanced Enneking stage." (PMID 38053170, 2023). "Together, these results indicated that the depletion of PSMD14 inhibited BC tumor growth in vitro and in vivo by targeting GPX4." (PMID 36632137, 2023). "The most significant finding was that the expression of PSMD14 was significantly correlated with increasing tumor diameter." (PMID 36632137, 2023). "PSMD14 was shown to fortify tumor cells against DNA-damaging drugs by promoting a switch from error-prone non-homologous end-joining to homologous recombination." (PMID 37892185, 2023).
tumor (continued). "There is increasing evidence that points to the importance of PSMD14 in tumor development and progression." (PMID 36632137, 2023). "PSMD14 showed significantly higher expression in tumors with larger diameters (tumor diameter >3 cm vs tumor diameter ≤3 cm; 85.14% vs 70.09%, P = 0.019)." (PMID 36632137, 2023). "Among them, three genes (RAB10, TCOF1, and PSMD14) were found to be significantly upregulated in tumor samples, and univariate Cox regression showed that they were also significantly associated with overall survival." (PMID 36171884, 2022). "PSMD14 was reported to promote cell proliferation in vitro and larger xenograft tumor formation in vivo." (PMID 35884607, 2022). "PSMD14 expression was significantly up-regulated in HCC tissues and was significantly associated with vascular invasion, tumor number, tumor recurrence and poor overall survival in HCC patients." (PMID 35937592, 2022). "PSMD14 inhibitor is, therefore, a safer and more effective candidate for tumor treatment with higher targeting capacity." (PMID 33456565, 2021). "In brief, these results above indicate that THL exerts anti-tumor effect in ESCC through PSMD14/SNAIL axis." (PMID 33897885, 2021). "We identified SNAIL target genes as an enriched pathway in the tumor specimens with high abundancy of PSMD14 from three ESCC cohorts by using Gene set enrichment analysis (GSEA)." (PMID 33897885, 2021). "Further, PSMD14 modulates tumor cell proliferation, through regulating the retinoblastoma protein (Rb) phosphorylation and cyclin-dependent kinases (CDKs)." (PMID 33805973, 2021). "Conversely, the tumor-promoting activity of PSMD14 in vivo was counteracted by the stable knockdown of E2F1." (PMID 33456565, 2021). "When the control SCC15 cells reached a tumor formation rate of 100% (7/7), even at a transplantation number of 1×104 cells per mouse, PSMD14-depleted SCC15 cells reached a tumor formation rate of only 14.3% (1/7) at the same dilution rate." (PMID 33456565, 2021). "In vivo growth was impaired in tumor formed by PSMD14 stable knockdown cells compared with tumor formed by the control cells." (PMID 34382324, 2021). "The anti-tumor activity of PSMD14 inhibitor Thiolutin was assessed by in vitro and in vivo experiments." (PMID 33456565, 2021). "We found that PSMD14 expression was significantly upregulated in LUAD tissues compared to the corresponding adjacent non-tumor tissues." (PMID 32226511, 2020). "The results showed that both the mRNA and protein levels of PSMD14 were markedly increased in tumor tissues compared to the controls." (PMID 32226511, 2020). "PSMD14 staining was primarily detected in the cytoplasm of normal cells whereas its staining was detected in both the cytoplasm and nuclei of tumor cells." (PMID 32226511, 2020). "Reduced PSMD14 expression inhibits tumor growth by inducing cell cycle arrest, senescence, or apoptosis." (PMID 32226511, 2020). "We also performed immunohistochemical staining to detect PSMD14 in tumor tissues and controls from LAUD patients." (PMID 32226511, 2020). "PSMD14 promotes cell growth and proliferation of gliomas, colon cancer, liver cancer, esophageal cancer, and breast cancer, and enhances the resistance of tumor cells to radiation and chemotherapy drugs 17-23." (PMID 32226511, 2020). "PSMD14 is involved in a series of important physiological and pathological processes such as DNA damage repair 13-16, tumor formation 17-19, and inflammation." (PMID 32226511, 2020). "Overexpression of PSMD14 correlates with vascular invasion, tumor recurrence, and poor tumor-free and overall survival in patients with HCC." (PMID 32268558, 2020). "Consistently, high PSMD14 levels were closely related to larger tumor size, lymph node metastases, and advanced TNM stage, with a predicted poor OS and DFS in LUAD patients." (PMID 32226511, 2020).
tumor (continued). "When PSMD14 is inhibited genetically or pharmacologically, IMPDH2 stability diminishes, causing impaired nucleotide metabolism, mitochondrial dysfunction, increased DNA damage signaling, and reduced tumor malignancy." (PMID 41608571, 2026). "The IHC scores for PSMD14 were considerably higher in PC tissues than in normal tissues and correlated with clinical stage, distant metastasis, neurological invasion, and tumor differentiation." (PMID 41051446, 2025). "PSMD14 promotes tumor metastasis through stabilizing SNAIL in ESCC." (PMID 40918133, 2025). "PSMD14 is involved in critical physiological and pathological events, including tumor growth." (PMID 40066751, 2025). "First, PSMD14 knockdown significantly reduced PC tumor volume and weight." (PMID 40066751, 2025). "Moreover, PSMD14 inhibitors have been reported to suppress tumor metastasis and enhance chemotherapy efficacy." (PMID 41488674, 2025). "In the TCGA dataset, the mRNA levels of PSMD14 were markedly increased in tumor tissues." (PMID 40475775, 2025). "In the tumor cohort, heightened PSMD14 expression was observed in DCs, tissue stem cells, endothelial cells, and epithelial cells, contrasting sharply with the limited expression noted in the control group, which emphasizes the potential role of PSMD14 in modulating the immune microenvironment." (PMID 40475775, 2025). "Importantly, the PSMD14 inhibitor Capzimin demonstrates significant anti-tumor activity, validating the therapeutic potential of targeting the PSMD14-HMMR axis." (PMID 41488674, 2025). "Moreover, our work reveals a pivotal role of PSMD14 in the formation of the immunosuppressive tumor microenvironment." (PMID 41488674, 2025). "Furthermore, in LUAD patients, PSMD14 expression was positively correlated with tumor stage (P = 0.033), with expression levels progressively increasing with advancing stage." (PMID 41488674, 2025). "Spearman correlation analysis revealed a significant negative correlation between PSMD14 expression and Tumor Immunity Cycle (TIP), scores in LUAD, suggesting that elevated PSMD14 levels may impair anti-tumor immune activity." (PMID 41488674, 2025). "Given nicotine’s established impact on tumor progression and immune responses, PSMD14 may act as a crucial mediator of these effects." (PMID 40475775, 2025). "Moreover, the ability of PSMD14 to regulate lipid metabolism in tumor cells was revealed for the first time." (PMID 41051446, 2025). "PSMD14 may affect tumor biology by influencing intracellular signaling pathways, facilitating tumor cell proliferation, and hindering apoptosis." (PMID 40475775, 2025). "PSMD14 is a deubiquitinating enzyme that may promote tumor progression by deubiquitinating different protein substrates." (PMID 40066751, 2025). "Furthermore, the discovery of new biomarkers like SSP1, PSMD14, and various metalloproteinases would help to elucidate our knowledge of tumor biology, as well as provide possible new targets for therapy." (PMID 39199313, 2024). "Additionally, our findings were confirmed in xenograft models, with PSMD14 depletion effectively inhibiting ERα positive tumor growth in vivo." (PMID 38017133, 2024). "In conclusion, our research showed that PSMD14 might be related to recurrence in HCC patients, and the expression of PSMD14 in tumor tissue might be a potential prognostic biomarker after tumor resection in HCC patients." (PMID 38327651, 2023). "Tumor volume (463.4 ± 222.27 mm3vs 1,026.4 ± 351.65 mm3, P = 0.002) and weight (0.766 ± 0.12 g vs 1.304 ± 0.21 g, P = 0.002) were markedly increased in the PSMD14-OE group compared to the control group." (PMID 36632137, 2023). "However, other mechanisms of PSMD14-mediated tumor progression, such as the immune microenvironment, remain elusive." (PMID 36959615, 2023).
tumor (continued). "Moreover, similar to CD320, the promoter methylation levels of SORT1 and PSMD14 were considerably lower in tumor tissues than in normal tissues, and there was also a negative correlation between gene expression and promoter methylation levels." (PMID 36959615, 2023). "Meanwhile, we conjectured that elevated PSMD14 may maintain tumor cell survival by stimulating autophagy enabling then to ensure their own energy metabolism as well as reduce damage under specific circumstances." (PMID 36959615, 2023). "Therefore, these clinical data suggested that tumors with PSMD14 overexpression in BC patients were significantly correlated with aggressive tumor characteristics." (PMID 36632137, 2023). "In addition, it has also been shown that PSMD14 can promote cell growth in vitro and tumor development in vivo." (PMID 37251574, 2023). "Previous studies have reported that PSMD14 is involved in a variety of biological processes, including cell viability, double-strand DNA break repair, cell differentiation, and tumor progression by regulating protein deubiquitination and stabilization." (PMID 36959615, 2023). "Tumor stemness is a major contributor to tumorigenesis and chemoresistance 23, 24, and even confers recurrence and poor prognosis 25, which has been proven to correlate with increased PSMD14." (PMID 33456565, 2021). "Furthermore, PSMD14 inhibitor Thiolutin exhibited a potent anti-tumor effect on HNSCC in vivo and in vitro by impairing DUB activity of PSMD14." (PMID 33456565, 2021). "Additionally, the rescue assays revealed that PSMD14 exerted tumor-promoting activity in HNSCC by regulating E2F1." (PMID 33456565, 2021). "On account of the in vitro and in vivo experiments results above, PSMD14 inhibitor, the one with higher targeting ability may be a safer and more effective candidate for tumor treatment." (PMID 33897885, 2021). "Moreover, abnormal overexpression of PSMD14 contributes to tumor growth and metastasis." (PMID 40016178, 2025). "The implications of these findings extend beyond simple correlation, indicating that PSMD14 may affect the tumor microenvironment and immune responses, thereby enhancing the understanding of the pathogenesis of LUAD while opening new pathways for therapeutic interventions." (PMID 40475775, 2025). "This research suggests that inhibiting PSMD14 may ameliorate PC by correcting tumor metabolism." (PMID 41051446, 2025). "Finally, PSMD14 knockdown in PC arrested tumor growth and lung metastasis." (PMID 40066751, 2025). "Furthermore, the results imply that PSMD14 may aid in tumor initiation and progression through the regulation of genes related to the cell cycle and its interactions with immune cells." (PMID 40475775, 2025). "In addition, we analyzed the association between the status of PSMD14 and various patient- and tumor-specific parameters to evaluate which patients might present with high expression of PSMD14." (PMID 36632137, 2023). "Therefore, PSMD14 could be a promising anticancer target used to inhibit tumor growth and block tumor metastasis." (PMID 36632137, 2023). "Therefore, THL exhibited potent anti-tumor activity in ESCC by impairing PSMD14 DUB function." (PMID 33897885, 2021). "Interestingly, our immune profiling revealed that PSMD14 high expression associates with an immunosuppressive microenvironment characterized by specific immune subtypes and reduced CD8+ T cell infiltration, suggesting its potential role in modulating anti-tumor immunity." (PMID 41488674, 2025). "With respect to the molecular mechanisms of PSMD14 in PC, we focused on exploring its role as a key deubiquitinase in the UPS and its regulatory mechanisms in tumor cell metabolism." (PMID 41051446, 2025). "The objective of this research was to explore the expression levels of PSMD14 in LUAD and to evaluate its potential implications for tumor immunity and clinical outcomes." (PMID 40475775, 2025).
tumor (continued). "Mechanistically, PSMD14 stabilizes lactate dehydrogenase (LDHA) through deubiquitination, leading to abnormally elevated lactate levels in tumor cells, which in turn drives increased lactylation at the H3K18 site (H3K18la)." (PMID 41051446, 2025). "Twelve of the ninety-nine DUB genes were identified as differentially expressed in MB compared to non-tumor tissue (p < 0.0001) for the GO category of DNA repair in the Swartling dataset, including USP1, OTUB1, UCHL5, USP7, and PSMD14 (aka POH1)." (PMID 37892185, 2023). "In this study, we validated the high expression of ATP6AP1, PSMD14 and HSP90AB1 in HCC tissue and the aberrant expression of PSMD14 in tumor tissue related to the poor prognosis." (PMID 38327651, 2023). "Then ATP6AP1, PSMD14 and HSP90AB1 were selected to verify the expression in 63 cases of tumor tissues and the adjacent non-tumor tissues." (PMID 38327651, 2023). "Then, we analyzed the relapse-free survival rate (RFS) of abnormal expression of ATP6AP1, PSMD14 and HSP90AB1 in these 63 HCC tissues and paired non-tumor tissues through five years of follow-up and in the K-M plotter database." (PMID 38327651, 2023). "PSMD14 knockdown has the potential to downregulate the PI3K/Akt/mTOR pathway, which was regarded as one of the key mechanisms promoting tumor growth." (PMID 38053170, 2023). "In this study, we found that THL dramatically suppressed the DUB activity of PSMD14 (with little effect on other JAMM DUBs) and E2F1/Akt/SOX2 pathway, which spurred tremendous interests to exploit THL as an anti-tumor drug." (PMID 33456565, 2021). "PSMD14 inhibitor O‐phenanthroline (OPA) effectively attenuated malignant behaviors of OV cells in vitro and OV tumor growth in vivo." (PMID 34382324, 2021). "Moreover, PSMD14-mediated E2F1 stabilization could promote tumor formation in liver cancer." (PMID 33897885, 2021). "In this study, we found that the level of PSMD14 was significantly upregulated in NSCLC tissues, suggesting its tumor-promoting effects in NSCLC." (PMID 32226511, 2020). "Although prior investigations have recognized various mechanisms of immune evasion, the exact correlation between PSMD14 expression, tumor immune infiltration, and patient outcomes in LUAD has not been comprehensively explored." (PMID 40475775, 2025). "This distinctive pattern of infiltration implies that PSMD14 may be instrumental in modulating the immune landscape of LUAD, potentially affecting tumor progression and mechanisms of immune evasion." (PMID 40475775, 2025). "Moreover, IHC analysis of LUAD specimens from the same source further confirmed the coordinated upregulation of both PSMD14 and HMMR in tumor tissues compared to adjacent normal regions." (PMID 41488674, 2025). "Additionally, a notable increase in PSMD14 protein levels was recorded in LUAD patients, with expression levels correlating with tumor size, lymph node involvement, and the TNM classification." (PMID 40475775, 2025). "The results indicated that CD320, PSMD14, and SORT1 protein levels were higher in tumor tissues than in normal tissues, while the level of NTF3 in the normal tissues was higher than that in the tumor tissues." (PMID 36959615, 2023). "We identified ATP6AP1, PSMD14 and HSP90AB1, which were exactly highly expressed in tumor tissue." (PMID 38327651, 2023). "The 26S proteasome non-ATPase regulatory subunit (PSMD) 2 (PSMD2), PSMD7, and PSMD14 proteins participate in the ubiquitin-proteasome system, which plays a potential role in the proliferation and progression of tumor cells." (PMID 37350936, 2023). "According to the results, ATP6AP1, PSMD14 and HSP90AB1, which are generally highly expressed in HCC tissue, were chosen and verified the expressions in 63 cases of HCC tissues and the paired adjacent non-tumor tissues." (PMID 38327651, 2023). "Although high expression of PSMD14 was more frequent in patients with tumor vascular invasion, there was no statistical significance (92.86% vs 74.85%, P > 0.05)." (PMID 36632137, 2023).